MPO (myeloperoxidase)
Diseases named in the same sentence as MPO in open-access papers (continued):
Sharing a sentence is not in itself a finding about the gene and the disease.
tumor (continued). "For the final diagnosis, immunohistochemistry (IHC) was performed, and the tumor cells tested positive for MPO, CD4, BCL-2, KI-67, and CD117 and negative for CD3, CD5, CD20, CD56, bcl-6, Mum-1, CD123, MUM-1, TdT, Syn, SOX11, and C-myc." (PMID 33120806, 2020). "MPO+, F4/80+ and CD20+ cells in tumor tissues were detected using immunohistochemistry." (PMID 32340025, 2020). "The granules contain myeloperoxidase (MPO), whose activity is required for the tumor cell killing." (PMID 33110073, 2020). "Specifically, a smaller tumor size was correlated with increases in CD45+CD11b+ cells present in the tumors (r = −0.956; p = 0.04), in serum MPO (r = −0.969; p = 0.03), in serum IL-5 (r = −0.948; p = 0.051), and in serum CXCL1 (r = −0.938; p = 0.06) concentrations." (PMID 31114758, 2019). "Injection of a luminol derivative (L-012) into the peritoneal cavity of tumour bearing mice lead to detection of MPO activity and ROS production at the tumour site whereas naive controls had no significant ROS production." (PMID 30504842, 2018). "Immunohistochemistry analysis of paraffin embedded tumor sections showed more abundant CD3+ and CD4+ T cells infiltrating NXS2, than Neuro2a tumors, while B220+ B cells and myeloid cells (identified by staining for myeloperoxidase) were similarly represented." (PMID 29070883, 2017). "The tumor-bearing mice displayed systemic signs of neutrophil activation and NET induction, as indicated by increased plasma levels of extracellular DNA and myeloperoxidase." (PMID 28743887, 2017). "For neutrophils, all, except three tumors, were completely negative for MPO (infiltration <5% of tumor area)." (PMID 28440285, 2017). "In CRC tissues, both colorectal epithelial cells (MPO negative) and tumor infiltrating myeloid cells (MPO positive) expressed FPR1." (PMID 28724995, 2017). "So, in principle, MPO inhibition should partially protect myeloid precursors from TOP2 poison-mediated DNA damage, while preserving the desired cytotoxic effects in the target tumor cells." (PMID 27974636, 2017). "Neutrophils could suppress tumor growth by releasing TRAIL and myeloperoxidase (MPO) in response to suitable stimuli." (PMID 28415700, 2017). "In situ analysis of MPO (neutrophils), F4/80 (macrophages) and B220 (B cells) expression on immunostained tumor sections did not indicate apparent differences between the two groups of mice (data not shown)." (PMID 29093489, 2017). "Finally, tumor-free areas of skin treated with CPAF exhibited a marked reduction in DMBA/PMA-induced inflammation, as assessed using myeloperoxidase (MPO activity), a marker of granulocytic cell infiltrates." (PMID 25375862, 2014). "In tumor-bearing state, G-CSF and IL-6 cooperated to enhance the potential of neutrophils to express Bv8 and MMP-9, and decrease the ability of neutrophils to release TRAIL, MPO and NE." (PMID 25587026, 2014). "In addition, transcripts of antimicrobial response effectors were less abundant in tumor tissue, with BPI, MPO and PRTN3 levels being significantly lower compared with those found in healthy tissue (p = 0.0133, p = 0.002 and p = 0.0022, respectively)." (PMID 24421902, 2014). "Dual color FISH analysis involving chromosome 17q showed that >10% of the cells from the tumor showed the deletion signal pattern of one red (NF1 region probe on 17q11) and two green [myeloperoxidase (MPO) gene region on 17q22 as the control probe), demonstrating a deletion of the NF1 gene." (PMID 24932270, 2014). "Immunohistochemically, Pax-5 was positive while terminal deoxynucleotidyl transferase (Tdt), CD3, and myeloperoxidase (MPO) were negative in tumor cells." (PMID 24385813, 2013). "The immunohistochemistry staining showed that the tumor cells were diffusely positive for S-100, CD1a, langerin and CD68, but negative for CD3, CD5, CD20, CD21, CD30, CD38, CD56, CD79a, ALK, HMB-45, Melan-A, pan-cytokeratin and MPO." (PMID 23388086, 2013).
tumor (continued). "However, HS presents negative markers of epithelial (epithelial membrane antigen or cytokeratin), melanocytic (CD34 or myeloperoxidase) and lymphoid (CD3 or CD20) neoplasms as in our case." (PMID 23668836, 2013). "In MYC/BCL-XL or MYC/BCL-2 mice tumor cells in spleen and liver expressed the myeloid marker MPO but not the T-cell markers." (PMID 22393362, 2012). "The tumor cells demonstrated positive reaction to myeloperoxidase (MPO), CD43 antibodies and negative to CD20 and CD2 monoclonal antibodies." (PMID 20624285, 2010). "At the same time, tumor cells were negative for MPO, CD99, NKX2.2 and CD61." (PMID 40565358, 2025). "In addition, it has been found that NE, MPO as well as MMP cleave vascular endothelial adhesion proteins, leading to impaired endothelial integrity, which in turn leads to vascular leakage and promotes tumor cell metastasis." (PMID 40979214, 2025). "In addition to MPO and NOX, neutrophil-independent sources of ROS such as monocytes, macrophages, or tumor cells may also drive L-012 signal, potentially confounding the observed in vivo correlation between ROS levels and NET markers." (PMID 41462673, 2025). "Additionally, no sex-based differences in tumor growth or survival between male and female WT and MPO−/− mice treated with and without ICT were observed." (PMID 38367056, 2024). "In addition, when MPO was examined through immunofluorescent staining, its transfer to tumor cells from d32Dcl3 neutrophils did not occur when these cells were not cultured together or were cocultured with the Boyden chamber." (PMID 38806658, 2024). "Experiments confirmed that MPO-deficient PMN-MDSCs did not affect cross-presentation by DCs, and the cross-presentation of tumour-related antigens by DCs in vivo was increased in MDSC-null or tumour-bearing MPO-KO mice." (PMID 37261073, 2023). "Overall, these data suggest that when 3-IAA and MPO are present during FIRINOX treatment, the accumulation of ROS increases and the stress adaptation of cancer cells is impaired (that is, autophagy is downregulated), ultimately inducing the reduced proliferation of tumour cells." (PMID 36813961, 2023). "In this study, histopathologic analysis of tissues collected from 80 patients with GC undergoing radical D2 resection showed significantly increased NET formation (MPO+/citH3+ cells) in tumour tissue samples compared with nontumor tissue samples from the same patient." (PMID 37127629, 2023). "We tried to further explore whether the tumor is progressive in patients with increased MPO; unfortunately, no prognostic data of tumors were extracted." (PMID 36551214, 2022). "However, when media was supplemented with 9-(S)-HODE (the product of MPO oxidation of LA), genetic reduction in MPO levels using Pxtf05258 mutants failed to decrease tumour incidence." (PMID 31992650, 2020). "In addition, we found that the presence of LYVE-1-positive cells (lymphatic vessels), MPO- positive cells neutrophils and CD206-positive cells macrophages was significantly increased in the orthotopic xenograft tumours of 44As3 in comparison to those of HSC-44PE." (PMID 31147602, 2019). "We postulate that MPO activity is required during the early phases of tumor initiation and promotion, while non-enzymatic functions of MPO play a role during later phases of tumor progression through protection of cancer cells against caspase-3 mediated cell death." (PMID 24821130, 2014). "However, during the later stages of tumor progression, MPO expression independent of catalytic activity appears to be required." (PMID 24821130, 2014). "Tumours developed in both groups, although, in the DSS group, the colonic mucosa appeared edematous and the number of haemorrhagic erosions and quantity of dysplastic lesions were higher as well as the mucosal concentration of myeloperoxidase and faecal viable count of Enterobacteriaceae." (PMID 22007198, 2011).
tumor (continued). "Although MPO deficiency results in limiting and loss of immunosuppressive myeloid cells causing in an overall reduction in immunosuppression within the tumor microenvironment, the low infiltration of T cells may not be sufficient to elicit an anti-tumor immune response in MPO−/− mice." (PMID 38367056, 2024). "Notably, MPO expression was significantly higher in tumor tissues than that in nontumor tissues." (PMID 33763491, 2021). "Our current finding revealed that DPP-4i enhanced tumor-infiltrating MPO+, CD4+, F4/80+, Foxp3+ cells, and MDSCs, but decreased CD8+ T lymphocytes in metastatic sites, indicating that DPP-4i may induce tumor-immunosuppressive microenvironment by enhancing tumor-infiltrating immune-suppressive cells." (PMID 34631556, 2021). "Thus, it is highly likely that the incompletely understood mechanisms by which cromolyn blocks mast cell degranulation mediated the anti-tumor effect observed here, rather than cromolyn also affecting monocytes, the production of the neutrophil product myeloperoxidase, and circulating growth." (PMID 31227713, 2019). "The ROS levels in both MPO−/− and PAD4−/− mice were similar and not significantly different from basal levels observed in tumor-free WT mice, suggesting that L-012 bioluminescence in this PDAC model primarily reflects NET formation." (PMID 41462673, 2025). "This was not seen for CD15+MPO− (CD15+; non-activated or immature neutrophils) (CD15+; P = 0.420), or CD15+ expression in malignant tumor cells (PFS CD15+ TC; P = 0.160)." (PMID 40652059, 2025). "The tumor cells were negative for CD25, myeloperoxidase (MPO), CD34, CD123, CD138, and CD163 but strongly positive for CD117, CD13, and CD33 and focally positive for mast cell tryptase, CD30, CD43, and CD68." (PMID 39404971, 2024). "In the presence of simvastatin, fluvastatin, or GGTI-298, but not YM-53601, tumor cells containing neutrophil-derived PKH26+ puncta and MPO+ granules were much fewer than in controls." (PMID 38806658, 2024). "FC did not correlate with any of the markers of local tumour inflammation (Klintrup–Mäkinen grade, lymphocytes, neutrophils, CD3, CD4, CD8, CD45, TIA-1, granzyme B and myeloperoxidase)." (PMID 35397505, 2022). "MPO expression in tumor tissues of LUAD and LUSC was much lower compared to its expression in healthy tissues (TPM < 2), and MPO was not expressed in NSCLC patients." (PMID 35227278, 2022). "Immunohistochemically, the tumor cells were negative for CD20, CD79a, CD3, CD5, c-kit, CD34, and TdT and positive for myeloperoxidase, CD33, CD68, and CD163." (PMID 34970464, 2021). "At a typical tumor concentration of 50 μM of H2O2, the changes of r1 values of the IO-Gd NVs were minimal either with or without the presence of MPO and NaCl." (PMID 32541769, 2020). "For the diagnosis of BPDCN, the tumor should be negative for other myelomonocytic, NK, T, and B lineage markers (CD34, CD8, MPO, lysozyme, PAX5, CD20, CD79a, EBV, and T-cell receptor protein)." (PMID 31752482, 2020). "In the present case, the pathomorphological examination was nonspecific, but IHC showed positive for EBER, MPO, CD4, BCL-2, CD117, which hinted that tumor cells were from the myeloid cells." (PMID 33120806, 2020). "Incisional biopsy of the gingival lesion displayed diffuse infiltration of undifferentiated tumor cells with granulocytic appearance, strongly immunopositive for CD99, myeloperoxidase and Ki-67 (60%), and negative for CD20, CD3, CD34 and TdT." (PMID 29075423, 2017). "The tumor cells were negative for a cluster of differentiation 3 (CD3), CD10, CD117, CD43, CD68, myeloperoxidase (MPO), lysozyme, multiple myeloma oncogene 1 (MUM-1), and CD138." (PMID 24755347, 2014). "The tumor cells were positive for CD117, CD34, myeloperoxidase and lysozyme, while negative for CD20, CD3, terminal deoxynucleotidyl transferase, CD99 and cytokeratin." (PMID 24377982, 2013).
tumor (continued). "Importantly, in accord with a previously published report we observed that MPO+ and CD15+ cells preferentially colonized CRC tissues while they poorly infiltrated normal colon mucosa, suggesting that they might be specifically recruited to the tumor microenvironment." (PMID 23734221, 2013). "Further immunohistochemical analyses revealed that F4/80-positive macrophages and MPO-positive neutrophils were decreased in KEAP1-KO tumors compared with WT tumors, although their spatial distribution within the tumor tissue was not affected by the KEAP1 deletion." (PMID 41035689, 2025). "Notably, trap–DNA structures, such as citrullinated H3 (cit H3) and myeloperoxidase (MPO), representing classical NETs were observed only in tumor tissues rather than DNTs, and these NETs were found to be primarily of neutrophil origin." (PMID 38790136, 2024). "This low number of T cells within the tumor microenvironment could account for the absence of discernible differences in KPCY6419 tumor growth in untreated WT and MPO−/− mice." (PMID 38367056, 2024). "Tumor immunophenotype was characterized by a strong expression of conventional myeloid antigens (CD13, CD33, CD15, MPO), although no monocytic (CD14, CD64, CD11c, CD11b, lysozyme), megakaryoblastic (CD61, CD41) and lymphoid (CD7, CD19, iCD79a, CD56, CD2) markers were found." (PMID 36980947, 2023). "Initially, the presence of CD4 and CD56 should be evaluated since only 8% of BPDCNs are negative for these, and their mere presence without other specific lineage markers such as CD19, cCD3, MPO, CD14, or CD64 with high HLA-DR should alert about the possibility of this type of neoplasm." (PMID 35530883, 2022). "Moreover, there was a positive correlation between macrophage infiltration and tumor sizes in SAs, PRLs, and NFPAs; however, there were no such correlations with CD4+ T cells, CD8+ T cells, or MPO+ neutrophils." (PMID 33664865, 2021).
cancer (215 papers, 2002 to 2026). A tumor composed of atypical neoplastic, often pleomorphic cells that invade other tissues. "Some studies suggest that markers more specific to NET formation, such as circulating MPO/DNA or NE/DNA complexes, as well as plasma levels of citrullinated histone H3 (H3Cit), are associated with poor prognosis in cancer patients." (PMID 40801632, 2025). "Neutrophils, for example, release myeloperoxidase and other mediators that exacerbate tissue damage and genomic instability, and their accumulation correlates with increased cancer risk." (PMID 40791849, 2025). "The purpose of this study was to determine the role of soluble P-selectin, NET, and MPO as risk factors for DVT in patients with malignancy receiving platinum-based chemotherapy." (PMID 39810847, 2024). "Elevated plasma MPO levels are associated with an increased risk of cardiotoxicity in DOX-treated cancer patients." (PMID 37656254, 2023). "Growing evidence has implicated myeloperoxidase (MPO), another granule protein, in the pathophysiology of different diseases including cancer." (PMID 37627581, 2023). "The effects of MPO in the context of cancer have gained attention recently, and MPO has been associated with various pro- and antitumor properties, but most evidence indicates that MPO is a molecule that promotes tumorigenesis and progression." (PMID 35326206, 2022). "HRs were reported in three publications to determine the connection between gal-3 and MPO, and the risk of cancer-therapy-related cardiotoxicity." (PMID 36551214, 2022). "The significant roles of MPO-463 G>A polymorphism were also reported in other cancers, including cervical, lung, breast, and bladder cancer." (PMID 34367972, 2021). "Carrying G/A or A/A genotype affects the expression of MPO and reduces the generation of oxygen radicals to decrease the risk of cancer." (PMID 34367972, 2021). "The MPO has been implicated in the initiation of neoplastic transformation in animal models of colitis-associated cancer and the enzyme expression indicates an increased risk for colorectal cancer (CRC) in humans." (PMID 33167555, 2020). "The expression of MPO has also been associated with ovarian epithelial carcinoma cells in early stage carcinomas." (PMID 32716937, 2020). "An abnormal MPO expression and greater risks of different forms of cancers are directly associated with MPO gene polymorphism." (PMID 29669993, 2018). "The strength of the association between MPO-463G > A polymorphism and cancer risk was estimated by odds ratios (OR) with 95% confidence interval (95%CI)." (PMID 28764808, 2017). "When stratified, in the HWE balanced group, the MPO-463G > A polymorphism was significantly associated with cancer risk in all the genetic models, while in the HWE un-balanced group, this association was only found in the recessive model and additive model." (PMID 28764808, 2017). "In total, significant association between MPO-463G > A polymorphism and cancer risk was observed under all the selected models when the eligible results were pooled together." (PMID 28764808, 2017). "This meta-analysis demonstrated a new subgroup (digestive system cancer group) to discussed the association between MPO-463G > A polymorphism and cancer risk in depth." (PMID 28764808, 2017). "The current analysis provided the most comprehensive investigation of MPO-463G > A polymorphism and cancer risk." (PMID 28764808, 2017). "Overall, in cumulative analysis, the stable trend indicated that evidence was sufficient to show the association between MPO-463G > A polymorphism and cancer risk." (PMID 28764808, 2017). "In order to further discuss the cancer risk of MPO-463G > A polymorphism, we divided digestive system cancer into digestive tract and digestive gland cancer." (PMID 28764808, 2017).